BRCA2 (BRCA2 DNA repair associated)
Diseases named in the same sentence as BRCA2 in open-access papers (continued):
Sharing a sentence is not in itself a finding about the gene and the disease.
cancer (continued). "We demonstrate that WRN helicase inhibition results in preferential cell killing of multiple BRCA2-deficient cancer cell lines with distinct tissue origins, suggesting an avenue of exploration for therapy." (PMID 34772932, 2021). "A point mutation at another site on BRCA2, D2723H, is cancer-prone and leads to cytoplasmic mis-localization of BRCA2 due to wrongly exposed nuclear export signals as a consequence of defective DSS1 binding." (PMID 34440403, 2021). "Based on the concept “synthetic lethality”, PARP inhibition can selectively lead to the death of BRCA1- or BRCA2-dysfunction cancer cells in which HR activity is deficient." (PMID 33397362, 2021). "Pathogenic BRCA1 and BRCA2 variants have been reported in 65–85% of cancer syndromes featuring high-grade serous ovarian carcinoma (HGSC), the most common histopathological subtype of epithelial OC, and in 10–20% of HGSC cases regardless of age at diagnosis." (PMID 34861889, 2021). "The positive predictive value of a PSA >3.0 ng/ml was higher in men with cancer-predisposing BRCA2 variants than in controls (31% vs 18%)." (PMID 34649841, 2021). "In this framework, we make the case for how the functional evaluation of VUS can be a powerful genetic tool not only for revealing novel aspects of BRCA2 function but also for re-evaluating cancer risk." (PMID 34359619, 2021). "Many patients with these specific cancer subtypes harbor somatic mutations in BRCA1 or BRCA2, or other homologous recombination (HR) genes, which inspired the development of targeted therapeutics." (PMID 33784323, 2021). "Most well-characterized variants causing a strong predisposition to cancer are mutated in the C-terminal 700 residues DNA binding domain of BRCA2." (PMID 34356684, 2021). "It would be interesting to uncover the mechanism by which MUS81 insufficiency leads to such different phenotypes between BRCA1- and BRCA2-deficient cancer cells." (PMID 33791310, 2021). "Despite their adjacent location in the C-terminal part of BRCA2 (and frequent simultaneous loss due to human cancer-predisposing mutations), DBD and CTD are functionally distinct." (PMID 34254584, 2021). "Even in the setting of inherited germline mutated BRCA1 or BRCA2, which is present in all the cells of the breast, only solitary cancers or at most multifocal cancers limited to 2 or 3 foci arise." (PMID 34044885, 2021). "A small molecule inhibitor of LIG1 (L82) was tested for synthetic lethality application in XRCC1, BRCA2 or ATM deficient cancer cells." (PMID 34373746, 2021). "Heterozygous mutation of BRCA2 is associated with an increased risk of developing cancers of the breast, ovaries, pancreas, and other sites, thus BRCA2 acts as a classic tumor suppressor gene." (PMID 34356050, 2021). "It should be noted that there is little genotype–phenotype correlation, apart from the greater severity of group D2 and the association of groups D1/BRCA2 and N with the occurrence of multiple and very early cancers." (PMID 33679882, 2021). "For example, we previously found that HSF2BP, when produced ectopically in somatic cancer cells, interferes with the role of BRCA2 in DNA interstrand crosslink repair by causing its degradation." (PMID 34326328, 2021). "We further demonstrated that WRNi-induced stalled forks undergo MRE11-mediated nucleolytic degradation in BRCA2-mutated cancer cells." (PMID 34772932, 2021). "The mechanisms of resistance in BRCA2-mutated cancers are much more than those, emerging evidence indicated that miRNAs are also involved." (PMID 33868274, 2021). "The authors concluded that associations of increased cancer risk due to BRCA2 c.9976A>T represented a reporting bias and this was due to the variant being in linkage with BRCA2 c.6275_6276delTT." (PMID 33672545, 2021). "Defects in HR, as exemplified by loss of BRCA1 or BRCA2 function, are associated with increased risk of breast, ovarian, prostate, pancreatic, and other cancers." (PMID 34481156, 2021).
cancer (continued). "In the pan-cancer analysis, we served BRCA2 as an esFARG, and BRCA2 had the most frequent mutation (29%)." (PMID 34869316, 2021). "A recent meta-analysis from the National Institute of Health identified a FANCD1/BRCA2 double mutated subset that showed a severe impairment of DNA damage response resulting in a cumulative incidence of cancer of 97% by age 7 years, including AML." (PMID 33802366, 2021). "One signature is associated with biallelic inactivation of BRCA1 and BRCA2 (due to HR deficiency) but has also been demonstrated in breast and pancreatic cancers from individuals with constitutional PALB2 truncating variants." (PMID 33854214, 2021). "Heterozygous germline mutations in BRCA2 confer a profound predisposition to breast, ovarian, pancreatic, prostate, fallopian tube, and other types of cancer, including melanoma." (PMID 34356050, 2021). "In this review we will investigate the recent literature associated with variants in the C-terminus of BRCA2 and their effect on health and cancer predisposition." (PMID 33503928, 2021). "L82 is selectively toxic in BRCA2 or ATM deficient HeLa cells: To evaluate if L82 is also selectively toxic in DSB repair deficient cancer cells, we tested in BRCA2 deficient HeLa and compared to controls." (PMID 34373746, 2021). "Germline mutations in BRCA1 or BRCA2 tumour suppressor genes predispose individuals to breast, ovarian, prostate and other types of cancer." (PMID 34389725, 2021). "This process occurs by the ready ability of aldehydes present at physiological concentrations to stimulate the degradation of BRCA2 protein, and hence predispose humans to cancer." (PMID 35071288, 2021). "Targeted inhibition of WRN helicase triggers heightened fork instability and reduces survival of BRCA2-mutated human cancer cells." (PMID 34772932, 2021). "Since the median age at cancer diagnosis in SMARCA4 mutation carriers is lower as compared to BRCA1/BRCA2 mutation carriers, the prophylactic surgery should be offered at least earlier, preferably below the age of 22." (PMID 33907931, 2021). "Germline pathogenic variants in the BRCA2 cancer susceptibility gene result in an increased lifetime risk of breast, ovarian, and other cancers." (PMID 34356684, 2021). "Several BRCA2 missense variants of uncertain clinical significance, which are reported in individuals with a hereditary cancer predisposition, localize to the highly conserved B56-interacting region (ClinVar database, NIH)." (PMID 34593815, 2021). "Typical assessment of BRCA2 deficiency on the genome involves cell-based models using cancer cells with mixed genetic contexts, but the role in normal tissue in vivo has not been clearly demonstrated." (PMID 34359565, 2021). "The subtype and hormone receptor status of a patient with BRCA2 mutation resembles that of sporadic cancer, but it is still associated with worse prognosis." (PMID 33996049, 2021). "We identify here a common mechanism underlying the pathogenicity of 9 out of 13 missense mutations in human BRCA2 classified as cancer-causing by expert panel review from amongst 37 known mis-sense mutations." (PMID 33978741, 2021). "Evidence supports that the predicted neo‐antigen load is higher in BRCA1‐ and BRCA2‐mutant and HR‐deficient cancers, owing to the theory that impaired DDR leads to genetic alterations and putative neo‐antigens, thus favoring recognition by the immune system." (PMID 33811746, 2021). "More recently, this inhibition was also shown to have antitumor activity with limited adverse side effects in cancer patients with BRCA1 or BRCA2 mutations." (PMID 34359565, 2021). "The relevance for such a system to understand BRCA2 function is appreciated due to the association of germline inheritance of a single mutated BRCA2 gene with the increased risk of developing certain cancers, particularly breast and ovarian." (PMID 34359565, 2021).
cancer (continued). "Simon is a 50 year old man who had a test two years ago via a genetics clinic for the cancer-predisposing BRCA2 variant identified in his sister." (PMID 34649841, 2021). "In the majority of cases, the BRCA1 or BRCA2 PVs are inherited from one of the parents accompanied by a cancer susceptibility transmitted as an autosomal dominant trait." (PMID 34026625, 2021). "We finally discuss the impact of cancer-associated variants on the function of BRCA2 IDRs and more generally on genome stability and cancer risk." (PMID 34356684, 2021). "Our findings identify a DSS1-mediated intracellular protein assembly mechanism that is disrupted by cancer-causing BRCA2 missense mutations, and suggest an approach for its therapeutic correction." (PMID 33978741, 2021). "Attenuation of WRN helicase results in enhanced fork degradation and defective fork restart in BRCA2-mutated cancer cells." (PMID 34772932, 2021). "Determining the precise effects of the SNPs in BRCA1 and BRCA2 mutation carriers will provide insights for understanding the biological basis of cancer development associated with BRCA1 and BRCA2 mutations." (PMID 33597508, 2021). "BRCA1/BRCA2 PV associated cancers were smaller overall with 75.0% and 85.4% being ≤ 20 mm respectively, potentially reflecting MRI screening in these groups." (PMID 34312777, 2021). "The tumor suppressor protein partner and localizer of BRCA2 (PALB2) orchestrates the interactions between breast cancer susceptibility proteins 1 and 2 (BRCA1, -2) that are critical for genome stability, homologous recombination (HR) and DNA repair." (PMID 34946951, 2021). "Failure to correct DNA damage in DNA repair defective cells, such as in BRCA1 and BRCA2 mutated backgrounds, is directly associated with increased cancer risk." (PMID 34830134, 2021). "Mutations of either BRCA1 or BRCA2 increase cancer risk in several different tumor types, including breast and ovarian, highlighting the importance of DSB repair factors in maintaining genome integrity and suppressing human diseases such as cancer." (PMID 34659365, 2021). "DDX11 loss greatly sensitizes both BRCA1- and BRCA2-deficient cancer cells to chemotherapeutic drugs, generating more DNA damage and genomic instability." (PMID 33879618, 2021). "BRCA2-deficient cells are sensitive to a range of established DNA damaging agents, many of which are used to treat cancer." (PMID 34356050, 2021). "Here, we identified a crucial role of WRN helicase to rescue stalled replication forks in cancer cells under genetic conditions of BRCA2 deficiency." (PMID 34772932, 2021). "Drug-driven synthetic lethality, fueled by the seminal discovery of PARPi-induced selective cytotoxicity in BRCA1- or BRCA2-deficient cancer cells, represents a paradigm for developing therapeutics by exploiting tumor-specific genetic deficiencies." (PMID 34772932, 2021). "Though 42 different pathogenic BRCA1 or BRCA2 variants have been identified in FC cancer families of Quebec, five recurrent pathogenic variants account for 84% of all mutation-positive BC and/or OC families." (PMID 34861889, 2021). "In this study, we revealed that curcumin is a potential RAD52 inhibitor that increases DNA damage sensitivity in BRCA2-deficient cancer." (PMID 33922657, 2021). "WRN is required to enact a timely restart following replication stalling and limit excessive degradation of stalled forks in BRCA2-deficient cancer cells." (PMID 34772932, 2021). "Genetic screens to detect deleterious mutations in BRCA2 are also important as a basis for personalized/precision cancer treatments." (PMID 34356050, 2021). "Individuals with identified pathogenic variants in the BRCA1/BRCA2 gene can benefit from cancer risk-reducing strategies." (PMID 34525964, 2021). "For example, restoration of BRCA1/BRCA2 activity due to reversion mutations, promoter demethylation, or the amplification of the mutant BRCA2 allele have all been associated with cancer resistance to PARPi." (PMID 33809714, 2021).
cancer (continued). "We tested for only BRCA1 and BRCA2 in the phase 1 of the project, but we are revising our policy to include other cancer susceptibility genes as well." (PMID 33920818, 2021). "As not all such cancer syndrome families are explained by BRCA1 and BRCA2, newly proposed gene candidates identified in other populations have been investigated for their role in conferring risk in French Canadian cancer families." (PMID 34298626, 2021). "Determination of the clinical relevance of rare germline variants of uncertain significance (VUSs) in the BRCA2 cancer predisposition gene remains a challenge as a result of limited availability of data for use in classification models." (PMID 33609447, 2021). "For instance, BRCA1 and BRCA2 show significant global variations according to contribution in regional cancer incidence and to mutation spectrum." (PMID 33827469, 2021). "Collectively, these results suggest that BRCA2 cancer mutations located in the B56-interacting region can deregulate the interaction to PP2A-B56 and sensitize cells to PARP inhibition." (PMID 34593815, 2021). "PALB2 is another gene of which bi-allelic germ line PGVs can cause FA, also termed FANCN, with a similar clinical presentation and cancer spectrum as FA caused by BRCA2 PGVs including childhood solid tumours." (PMID 34680915, 2021). "Dual loss of BRCA2 and MUS81 results in obvious cancer cell death, indicating a pivotal role of MUS81 in BRCA2-mutated cancer cells." (PMID 33791310, 2021). "Knowledge of the functions of domains throughout BRCA2 is also necessary for developing and/or implementing effective cancer prevention measures and specific treatments based upon the mutational status and residual function(s) of BRCA2 in cells." (PMID 34356050, 2021). "Considering the distinct molecular roles of BRCA1 and BRCA2, it is understandable that the pathogenic variants of BRCA1 and BRCA2 are associated with different subtypes in cancers." (PMID 35008774, 2021). "BRCA2 mutations found to increase cancer risk consist of indels, frameshifts, and nonsense mutations, ultimately leading to loss of expression or a truncated protein product." (PMID 34065235, 2021). "A class of drugs called PARP inhibitors, which block the repair of DNA damage, have been found to arrest the growth of cancer cells that have pathogenic BRCA1 or BRCA2 variants." (PMID 34207450, 2021). "Through clonogenic survival assays, we found that curcumin increased the sensitivity of Capan1 cells to CPT-11, which is consistent with previous results that curcumin sensitizes BRCA2-deficient cancer cells to DNA damaging drugs." (PMID 33922657, 2021). "Heterozygous carriers of germline pathogenic variants in either BRCA1 or BRCA2 are at significantly increased lifetime risk of breast and other cancers, with risk accruing from a young age." (PMID 34771713, 2021). "There is evidence from two large pan-cancer analyses suggesting that checkpoint inhibitors are more effective in patients with BRCA2-mutated tumors." (PMID 34067105, 2021). "The tumor suppressor BRCA2 functions as a central caretaker of genome stability, and individuals who carry BRCA2 mutations are predisposed to breast, ovarian, and other cancers." (PMID 34440403, 2021). "Inherited BRCA1 and BRCA2 mutations are associated with increased lifetime risks of breast and ovarian cancers by 45–75% and 18–40%, respectively, as well as other cancers like pancreatic and prostate cancers." (PMID 34206661, 2021). "First-line maintenance treatment with PARPi is available through the Cancer Drugs Fund for people with a BRCA1 or BRCA2 gene mutation." (PMID 33808557, 2021).
cancer (continued). "Here, we exploited a series of computational and biochemical assays to discover and characterize specific RAD52 inhibitors inducing synthetic lethality in BRCA2-mutated cancer cells." (PMID 33995041, 2021). "With the identification of BRCA1 and BRCA2, their roles in conferring risk for BC and OC in various populations were investigated by targeted gene sequencing analyses of cancer cases." (PMID 34298626, 2021). "Over the past 25 years since the discovery of BRCA1 and BRCA2, it is increasingly clear that FCs of Quebec, Canada have played a significant role in defining the genetic landscape of cancer predisposing genes." (PMID 34298626, 2021). "Pharmacological inhibition of WRN helicase preferentially kills BRCA2-deficient cancer cells and sensitizes them to the PARP inhibitor olaparib." (PMID 34772932, 2021). "Forty-five (13.9%) had at least one cancer diagnosis, the majority of whom harbored a BRCA2 mutation (75.5%)." (PMID 34575694, 2021). "PARPi is an effective therapeutic agent against BRCA1- and BRCA2-associated cancers, as BRCA mutations lead to DNA double-strand breaks that cannot be efficiently repaired, thus leading to the death of cancer cells." (PMID 33609766, 2021). "Our observation is in line with a study that measured a total of 20% of BRCA1 or BRCA2 deleterious germline mutations on forty Algerian primary invasive unrelated BC cases who attended the Anti-Cancer Center of Setif." (PMID 32102524, 2020). "Conversely, the BRCA2-9254del5 founder mutation originating in the Northeast Spanish was observed in 6 Sicilian subjects, including 3 cancer patients, from the city of Palermo." (PMID 32380732, 2020). "Women carrying pathogenic BRCA1 or BRCA2 variants have different opportunities to manage their cancer risk." (PMID 33031463, 2020). "Even in the setting of inherited germline mutated BRCA1 or BRCA2, which is present in all the cells of the breast, only solitary cancers or multifocal cancers limited to 2 or 3 foci at most arise." (PMID 33196707, 2020). "This was independent from the type of germline mutation, BRCA1 or BRCA2 and was true for both types of cancers when analyzed independently." (PMID 32164626, 2020). "The mutational signature for BRCA1/BRCA2 mutations, or Signature 3, was reconfirmed in this study, and documented in version 2 of the Catalog of Somatic Mutations in Cancer (COSMIC) mutational signatures." (PMID 32269964, 2020). "Approximately 30% of this hereditary cancer risk is explained by genetic variants in high-penetrance susceptibility genes such as BRCA1 or BRCA2." (PMID 33198123, 2020). "Prior studies have also observed an association between POLQ overexpression in cancer with BRCA1/BRCA2 mutation and an over-representation of TMEJ-associated genomic scars." (PMID 33385162, 2020). "Genetic testing for BRCA1 and BRCA2 pathogenic variants has become an important part of clinical practice for cancer risk assessment and for reducing individual risk of developing cancer." (PMID 33081408, 2020). "The current study provides further evidence that risk-reducing surgery is beneficial in reducing cancer-related distress in women with a BRCA1 or BRCA2 mutation." (PMID 32393849, 2020). "Loss of BRCA2 results in defective repair, which when prolonged, can accumulate a lethal amount of damaged DNA causing cancer or apoptosis." (PMID 32638521, 2020). "Our results show that the mutation frequency was 4.1% in BRCA1 and BRCA2 and 5.4% in other cancer genes." (PMID 31963545, 2020). "This phenomenon, known as synthetic lethality, is exhibited by cancers with biallelic mutations in HR genes such as BRCA1 or BRCA2." (PMID 33002095, 2020). "BRCA1 and BRCA2 mutations are relatively frequent in patients who have a family history of cancer, i.e., hereditary breast and ovarian cancer." (PMID 32098267, 2020).